RSL24D1 (ribosomal L24 domain containing 1)
Description:
Involved in the biogenesis of the 60S ribosomal subunit. Ensures the docking of GTPBP4/NOG1 to pre-60S particles (By similarity).
Synonyms: C15orf15; RPL24L; HRP-L30-iso; L30; RPL24; RLP24; TVAS3
Tractability: Small molecule: a structure with a bound ligand is known. PROTAC: ubiquitination databases record sites on it; its protein half-life has been measured.
Gene: Protein-coding gene on chromosome 15 (55,180,797 to 55,197,076, reverse strand). Ensembl gene ENSG00000137876.
Subcellular location: Nucleus, nucleolus
Subcellular location (Human Protein Atlas): Nucleoli; Nucleoli rim; Nucleoplasm
Gene Ontology:
Molecular function: protein binding; structural constituent of ribosome
Biological process: ribosomal large subunit biogenesis
Cellular component: nucleolus; nucleoplasm
Genetic constraint (gnomAD): Loss-of-function variants: 1 observed, 8.69 expected, observed/expected ratio (o/e) 0.12, 90% interval 0.04 to 0.55. That is too few expected variants to judge how well the gene tolerates losing a copy. Missense variants: 109 observed, 122.76 expected, observed/expected ratio (o/e) 0.89, 90% interval 0.76 to 1.04. Synonymous variants: 42 observed, 37.83 expected, observed/expected ratio (o/e) 1.11, 90% interval 0.87 to 1.44.
Homologues: Orthologues: chimpanzee RSL24D1 (100% identical), macaque RSL24D1 (100% identical), mouse Rsl24d1 (98% identical), rat Rsl24d1 (98% identical), guinea pig RSL24D1 (98% identical), pig RSL24D1 (88% identical), tropical clawed frog rsl24d1 (88% identical), dog RSL24D1 (87% identical), zebrafish rsl24d1 (79% identical), rabbit RSL24D1 (71% identical), Drosophila melanogaster RpL24-like (60% identical), Caenorhabditis elegans rpl-24.2 (50% identical). Paralogues in human: RPL24 (30% identical).
Diseases named in the same sentence as RSL24D1 in open-access papers:
RSL24D1 is named in the same sentence as 16 diseases in open-access papers, as found by Europe PMC text mining. Sharing a sentence is not in itself a finding about the gene and the disease. The quoted sentences say what the papers report.
breast carcinoma (1 paper, 2021). "Our study found that RSL24D1 in TEPs was negatively associated with cancers at an early stage, including breast cancer, lung cancer, CRC, PAAD, and HBC, compared to healthy controls." (PMID 33955587, 2021).
Eμ (1 paper, 2016). "Nevertheless, control shRNAs targeting essential genes (Rpa1, Rpa3 and Polr2b;) were consistently depleted in all four replicates, as were shRNAs targeting genes that either cooperated with Myc (Prmt5 and Odc) or belonged to known oncogenic pathways in Eμ-myc lymphomas (Adsl and Rsl24d1)." (PMID 27635472, 2016).
familial hypercholesterolemia (1 paper, 2019). An inheritable form of hyperlipidemia, in which there are excess lipids in the blood. "RSL24D1 has been identified as a potential target in familial hypercholesterolemia." (PMID 31296617, 2019).
glioblastoma (1 paper, 2022). The most malignant astrocytic tumor (WHO grade IV). "Eight genes associated with glioblastoma prognosis were identified based on LASSO analysis: RPS10, RPS11, RPS19, RSL24D1, RPL39L, EIF3E, NUDT5, and RPF1." (PMID 36733371, 2022). "Eight genes—RPS10, RPS11, RPS19, RSL24D1, RPL39L, EIF3E, NUDT5, and RPF—were found to have an expression in the prognosis of glioblastoma." (PMID 36733371, 2022).
cancer (2 papers, 2019 to 2021). A tumor composed of atypical neoplastic, often pleomorphic cells that invade other tissues. "In this study, 7 TEPs mRNAs were verified, including RSL24D1, IFI27, CRYM, HBD, IFITM3, FCGR2A, and KLHDC8B, which may be used for cancer detection." (PMID 33955587, 2021). "Consequently, we believe alternative TEPs mRNAs, including RSL24D1, IFI27, CRYM, HBD, IFITM3, FCGR2A, and KLHDC8B mRNA, can potentially serve as non‐invasive biomarkers for diagnosing cancers and can even predict the prognosis of pan‐cancer." (PMID 33955587, 2021). "Seven TEPs mRNAs were discovered in our study: RSL24D1, IFI27, CRYM, HBD, IFITM3, FCGR2A, and KLHDC8B in TEPs, which are mainly enriched in protein binding, extracellular matrix, and metabolic process, and may be used for cancer diagnosis." (PMID 33955587, 2021).
RSL24D1 also shares sentences with these, for which no sentence is quoted: adenocarcinoma (1 paper); bacterial infection (1); COVID-19 (1); developmental delay (1); lung carcinoma (1); lymphoma (1); metastatic tumor (1); microcephaly (1); pancreatic cancer (1); Stroke (1); tumor (1).